S1PR4 (sphingosine-1-phosphate receptor 4)
Description:
G protein-coupled receptor highly expressed in immune cells, where it regulates immune response and cytokine production. Functions as a receptor for the lysosphingolipid sphingosine-1-phosphate (S1P). Upon S1P binding, promotes regulatory T-cell differentiation and enhances fatty acid oxidation, through activation of the NRF2/PPARA signaling pathway (By similarity). Modulates also M1 macrophage activation through interaction with FPR2 and the JNK signaling, contributing to the inflammatory response (By similarity). In addition, facilitates early neutrophil mobilization and vascular activation during inflammation, promoting lymphocyte recruitment to draining lymph nodes and supporting the development of germinal centers for an effective adaptive immune response (By similarity).
Synonyms: S1P4; EDG6; LPC1; SLP4
Tractability: Small molecule: an approved drug acts on it; a high-quality ligand is known; it belongs to a druggable protein family. Antibody: its Gene Ontology location is reachable by antibodies, with high confidence; UniProt places it where antibodies can reach, with medium confidence; UniProt predicts a signal peptide or a membrane-spanning region. PROTAC: its protein half-life has been measured; a small molecule that binds it is known.
Target class: EDG receptor; Family A G protein-coupled receptor; Lipid-like ligand receptor (family A GPCR); Membrane receptor; Small molecule receptor (family A GPCR)
Chemical probes: ML-178 (high quality), ML131 (high quality), ML248
Gene: Protein-coding gene on chromosome 19 (3,172,346 to 3,180,332, forward strand). Ensembl gene ENSG00000125910.
Subcellular location: Cell membrane
Subcellular location (Human Protein Atlas): Mitochondria
Pathways (Reactome):
Signal Transduction: G alpha (i) signalling events; Lysosphingolipid and LPA receptors
Gene Ontology:
Molecular function: protein binding; G protein-coupled receptor activity; lipid binding; sphingosine-1-phosphate receptor activity
Biological process: G protein-coupled receptor signaling pathway; sphingosine-1-phosphate receptor signaling pathway; adenylate cyclase-activating G protein-coupled receptor signaling pathway
Cellular component: mitochondrion; cytoplasm; plasma membrane; membrane; presynapse
Genetic constraint (gnomAD): Loss-of-function variants: 1 observed, 0.99 expected, observed/expected ratio (o/e) 1.01, 90% interval 0.27 to 1.89. That is too few expected variants to judge how well the gene tolerates losing a copy. Missense variants: 595 observed, 535.1 expected, observed/expected ratio (o/e) 1.11, 90% interval 1.04 to 1.19. Synonymous variants: 296 observed, 249.07 expected, observed/expected ratio (o/e) 1.19, 90% interval 1.08 to 1.31.
Homologues: Orthologues: dog S1PR4 (86% identical), pig S1PR4 (86% identical), mouse S1pr4 (82% identical), rat S1pr4 (82% identical), tropical clawed frog s1pr4 (50% identical), zebrafish s1pr4 (46% identical). Paralogues in human: S1PR5 (38% identical), S1PR3 (37% identical), S1PR1 (36% identical), S1PR2 (33% identical), LPAR2 (31% identical), LPAR1 (28% identical), LPAR3 (27% identical), CNR1 (23% identical), GPR3 (21% identical), GPR12 (21% identical), GPR6 (20% identical), CNR2 (20% identical), and 6 more.
Diseases named in the same sentence as S1PR4 in open-access papers:
S1PR4 is named in the same sentence as 59 diseases in open-access papers, as found by Europe PMC text mining. Sharing a sentence is not in itself a finding about the gene and the disease. The quoted sentences say what the papers report.
breast cancer (16 papers, 2012 to 2025). A primary or metastatic malignant neoplasm involving the breast. "S1PR4 and high expression of SphK1 are associated with shorter survival in breast cancer patients, indicating the importance of S1PR4 and SphK1 in the progression of breast cancer." (PMID 38542328, 2024). "High S1PR3 and S1PR4-5 are causally associated with poorer survival in breast cancer." (PMID 28869494, 2017). "S1P released by dying MCF-7 breast cancer cells activated S1PR4 on human DCs to release IL-27, which in turn triggered Tregs to suppress CD8+ T cell function, leading to reduced tumor cell killing." (PMID 35163211, 2022). "Many have also attempted to investigate the involvement of S1PRs in the signaling cascades of SPHK1/S1P axis in human cancers, whereby substantial evidence has highlighted the interactions between SPHK1/S1P axis with S1PR1, S1PR3, and S1PR4 in breast cancer." (PMID 34820423, 2021). "HER2 overexpression is a major determinant of breast cancer progression, and S1P signaling may contribute to this; S1PR4 stimulates the ERK1/2 pathway in ER-negative HER2-positive MDA-MB-453 breast cancer cells through a HER2-dependent mechanism." (PMID 38542328, 2024). "Indeed, in murine tumor models of CAC and especially in breast cancer upon standard-of-care chemotherapy, S1PR4 ablation resulted in significantly reduced tumor growth through enhanced CD8+ T cell proliferation." (PMID 35163211, 2022). "The depletion of S1PR4 was shown to inhibit mammary tumor progression in vivo via CD8+ T-cell expansion, since S1PR4 signaling promotes tumor growth by inhibiting CD8+ T-cell abundance." (PMID 35565311, 2022). "Furthermore, for S1PR4, it has been reported to regulate migration and invasion pathways via epidermal growth factor receptor 2 (HER2) in breast cancer." (PMID 37038210, 2023). "In a study on human breast cancer cells, JTE013 was also found to inhibit an S1PR4 antagonist." (PMID 37038210, 2023). "Interestingly, we detected S1PR2 expression in the membrane, cytoplasm and nucleus of tumour cells and it has been shown recently that S1PR4 functions to prevent nuclear accumulation of S1PR2 to enhance the growth of ER negative breast cancer cells." (PMID 27160553, 2016). "Interestingly, S1PR4 in these cells did not affect ERK1/2 activation, which might have counteracted the negative effect of S1PR4 on myoblast survival, as indicated for breast cancer cells." (PMID 28848247, 2017). "However, the study did not reveal S1PR2, S1PR4 mRNA, or protein levels in MDA-MB-453 breast cancer cells treated with JTE013." (PMID 34769490, 2021).
colitis (5 papers, 2017 to 2025). Inflammation of the colon. "IL-6 levels were also reduced in serum of S1PR4-deficient mice suffering from inflammatory DSS-induced colitis, which is Th17-dependent." (PMID 28848247, 2017). "Although S1PR4 deficiency showed a major improvement of DSS-induced colitis, inflammatory bowel disease (IBD) in humans does not appear to be strictly Th17-dependent." (PMID 28848247, 2017).
psoriasis (5 papers, 2017 to 2025). An autoimmune condition characterized by red, well-delineated plaques with silvery scales that are usually on the extensor surfaces and scalp. "Nevertheless, these data suggest that S1PR4 harbors the potential to be a feasible target for affecting disease progression of Th17-driven immune-mediated diseases such as psoriasis, asthma, and inflammatory bowel disease." (PMID 28848247, 2017). "Beside these speculations, further investigations are required to clearly dissect the role of S1PR4 in cytokine production in disease models including psoriasis, rheumatoid arthritis, SLE, and cancer." (PMID 28848247, 2017). "Ponesimod, a selective modulator of S1PR1, S1PR4, and S1PR5, has been tested in a phase 2 study in psoriasis." (PMID 36674974, 2023).
asthma (4 papers, 2022 to 2025). "On the basis of the findings above, we aimed to dissect the effect of S1PR4 on asthma by treating S1pr4-KO and WT mice with OVA/LPS induction." (PMID 37056936, 2023). "Lastly, further research is necessary to completely elucidate the effects of S1PR4 on the function of other immune cells in the pathogenesis of asthma." (PMID 37056936, 2023). "To verify these results, we examined the expression of S1PR4 in the lungs of asthma patients and HC subjects." (PMID 37056936, 2023). "Firstly, we employed a relatively small asthma cohort and more asthma patients with different endotypes are needed to verify the disturbance of sphingosine metabolism as well as the expression of S1PR4." (PMID 37056936, 2023). "Among our genes that were driven by rare variants, i.e., ALOX15, CSF2RB, IL17RA, IL33, JAK2, S1PR4, and SH2B3, previous studies supported a rare variant association between IL33, which is a known asthma locus, and eosinophil count." (PMID 35935937, 2022). "In our study, S1PR1 and S1PR4 were the main receptors expressed in asthmatic PBMCs, while S1PR4 was the only elevated receptor after standardized management and treatment of asthma, indicating to a predictable effect on the pathophysiology of asthma, especially in the immune response." (PMID 37056936, 2023). "Furthermore, the expression changes in PBMCs before and after asthmatic treatment were compared and the results indicated that S1PR4 was the only elevated receptor after standardized management and treatment of asthma." (PMID 37056936, 2023). "We conducted further experiments with patients and mice to elucidate the impact of S1PR4, a GPCR for bioactive sphingosine metabolites, on the pathogenesis of asthma." (PMID 37056936, 2023). "Our research indicates S1PR4 a promising therapeutic target for non-eosinophilic phenotypes of asthma." (PMID 37056936, 2023). "In summary, we have demonstrated that a disturbance in sphingosine metabolism existed in asthma patients independent of different endotypes while the crucial sphingosine receptor S1PR4 was altered in patients and experimental mice, especially those with neutrophilic airway inflammation." (PMID 37056936, 2023). "In brief, the findings of this study substantiate the hypothesis that targeting S1PR4 may be a promising therapeutic approach for non-eosinophilic phenotypes (refractory or ICS-insensitive) of asthma in clinical settings." (PMID 37056936, 2023).
atherosclerosis (3 papers, 2017 to 2022). A disease characterized by the build-up of fatty material and calcium deposition in the arterial wall resulting in partial or complete occlusion of the arterial lumen. "Although these findings may suggest an indirect involvement of S1PR4 and S1PR5 in atherosclerosis-associated inflammation, the latter receptors seem to have less of a direct impact on atherosclerosis pathology." (PMID 36233252, 2022). "Additionally, the finding that FTY20 inhibited S1PR3 and S1PR4 in macrophage foam cells was similar to previous reports that FTY20 could suppress S1PR1 and S1PR3 to decrease inflammatory factors and alleviate atherosclerosis." (PMID 30627532, 2018).
metabolic dysfunction-associated steatohepatitis (3 papers, 2023 to 2025). Metabolic dysfunction-associated steatohepatitis (MASH, formerly known as nonalcoholic steatohepatitis or NASH) is a type of fatty liver disease. "Among them, S1PR1 controls the expression of IL-1β in response to Newcastle disease virus by modulating the NLRP3/caspase-1 inflammasome pathway and enhances inflammation and fibrosis in the kidney, while S1PR4 promotes nonalcoholic steatohepatitis by activating NLRP3 inflammasomes." (PMID 38003456, 2023).
Sepsis (3 papers, 2021 to 2024). Sepsis is defined as life-threatening organ dysfunction caused by a dysregulated host response to infection. "Although a recent report found that S1PR4-deficiency in a sepsis model caused reduced splenic GC formation, the mechanisms leading to these abnormalities were ambiguous." (PMID 39188715, 2024). "After sepsis induction, the germinal center response was severely impaired in S1PR4-deficient animals." (PMID 36532028, 2022). "In order to test whether this process is affected by S1PR4-deficiency, the localization of MZ B cells was assessed before, one and seven days after sepsis induction." (PMID 36532028, 2022). "With fewer effector cells available to seed cognate interactions, we conclude that S1PR4-/- mice ultimately develop a limited number of GC reactions in the dLN, similar to the reduced splenic follicle sizes in the sepsis model described by Riese." (PMID 39188715, 2024). "Before sepsis induction, both s1pr4−/− and wt MZ B cells were present at their usual localization in the follicle periphery." (PMID 36532028, 2022). "In contrast to sterile LPS-induced peritonitis, peritoneal B1a B cell numbers were significantly reduced in s1pr4−/− mice when compared to the wt control animals both 24 h and 7 days after sepsis induction." (PMID 33801658, 2021). "The sepsis induced early antibody response – which is predominantly T cell independent – was not affected by S1PR4 deficiency." (PMID 36532028, 2022).
colorectal cancer (2 papers, 2021 to 2023). A primary or metastatic malignant neoplasm that affects the colon or rectum. "From previous studies, we identified CCXR2 and S1PR4 as the factors affecting the infiltration of T cells CD8 in colorectal carcinoma." (PMID 38049474, 2023).
gastric cancer (2 papers, 2021 to 2022). A primary or metastatic malignant neoplasm involving the stomach. "Furthermore, limited information is available on the roles of S1PR4 and S1PR5 in gastric cancer, indicating the need to further reveal it." (PMID 34831211, 2021).
lung carcinoma (2 papers, 2022 to 2023). "We found that lung cancer tissues expressed mainly S1PR1, S1PR2 and S1PR3, whereas S1PR4 and S1PR5 were undetectable, probably because they are highly restricted to distinct cell types and tissues, such as the lymphoid tissues, brain, and spleen." (PMID 37446018, 2023). "Indeed, we demonstrated that S1PR1, S1PR2, S1PR3, and S1PR5, but not S1PR4 are correlated with worse lung cancer patient prognosis." (PMID 35897763, 2022).
peritonitis (2 papers, 2021 to 2024). Inflammation of the peritoneum (tissue that lines the abdominal wall and covers most of the organs in the abdomen). "A recent publication reported reduced splenic GC formation in S1PR4-/- mice following colon ascendens stent peritonitis (CASP)." (PMID 39188715, 2024). "In the model of sterile LPS‐induced peritonitis, there were significantly fewer labeled GM-CSF-positive s1pr4−/− IRA B cells than wt IRA B cells found in the spleen." (PMID 33801658, 2021).
anaphylaxis (1 paper, 2018). An acute hypersensitivity reaction that occurs from exposure to an allergen. "As it will be shown, global genetic deletion of S1pr4 resulted in exacerbation of IgE-mediated systemic anaphylaxis, although S1P4 was dispensable for normal FcεRI-mediated activation in S1pr4-deficient cultured mast cells." (PMID 29693558, 2018). "S1pr4−/− mice exhibited increased hypothermia compared with S1pr4+/+ controls that was most apparent early on and was maintained throughout the course of induced anaphylaxis." (PMID 29693558, 2018).
autoimmune disease (1 paper, 2017). A disorder resulting from loss of function or tissue destruction of an organ or multiple organs, arising from humoral or cellular immune responses of the individual to their own tissue constituents. "Moreover, S1PR4 signaling suppressed IFN-α production from pDCs, which by itself is a potent driver of certain autoimmune diseases." (PMID 28848247, 2017).
chronic lymphocytic leukemia (1 paper, 2016). "In addition, the modulation of S1PR1, S1PR2, and S1PR4 engagement regulates B cell circulation in patients with chronic lymphocytic leukemia (CLL)." (PMID 27800303, 2016).
colorectal adenocarcinoma (1 paper, 2023). The most common type of colorectal carcinoma. "Thus, our results demonstrate that the low-risk group could reverse the T cells CD8 infiltration by up-regulating the expression of CCXR2 and S1PR4 in female patients with advanced colorectal adenocarcinoma." (PMID 38049474, 2023). "Consequently, the infiltration level of T CD8 cells could be reversed by the overexpression of CCXR2 and S1PR4 in female advanced colorectal adenocarcinoma patients." (PMID 38049474, 2023).
Crohn disease (1 paper, 2017). A gastrointestinal disorder characterized by chronic inflammation involving all layers of the intestinal wall, noncaseating granulomas affecting the intestinal wall and regional lymph nodes, and transmural fibrosis. "In fact, neutralizing IL-17 has even shown an adverse effect in patients with Crohn's disease, probably limiting the applicability of targeting S1PR4 to treat IBD." (PMID 28848247, 2017).
hyperlipidemia (1 paper, 2019). "All these data demonstrate that NCF2, MYO1F, S1PR4, and FCN1 in PBMC combination with sex and hyperlipidemia could be diagnostic biomarkers for obstructive CAD." (PMID 31245869, 2019). "Subsequent analysis of the diagnostic value of these genes in obstructive CAD further confirmed that NCF2, MYO1F, S1PR4, and FCN1 together with risk factors, gender, and hyperlipidemia, could improve the diagnostic accuracy of distinguishing obstructive CAD from free of obstructive CAD." (PMID 31245869, 2019).
injury (1 paper, 2025). Damage inflicted on the body as the direct or indirect result of an external force, with or without disruption of structural continuity. "We hypothesize that Ks extracts may exert protective effects against APAP-induced acute liver injury by modulating the SPHK1/S1P/S1PR2/S1PR4 pathway and the Nrf2/Keap1 pathway, thereby mediating oxidative stress and inflammatory responses." (PMID 40811614, 2025).
ischemia reperfusion injury (1 paper, 2017). Adverse functional, metabolic, or structural changes in ischemic tissues resulting from the restoration of blood flow to the tissue (reperfusion), including swelling; hemorrhage; necrosis; and damage from free radicals. "Multiple studies demonstrated a protective effect in ischemia-reperfusion injury using fingolimod (agonist for S1PR1, S1PR3, S1PR4, and S1PR5) in different organs including the heart." (PMID 28596734, 2017).
metabolic syndrome (1 paper, 2024). A cluster of metabolic risk factors for CARDIOVASCULAR DISEASES and TYPE 2 DIABETES MELLITUS. "Furthermore, S1PR4 levels were also decreased in the cortex of a diet-induced obese mouse model with metabolic syndrome, along with increased cortical levels of S1P." (PMID 37794263, 2024).
ovarian carcinoma (1 paper, 2019). A malignant neoplasm originating from the surface ovarian epithelium. "This discovery acts as starting point to clarify the functionality of S1PR4 and the contribution of S1P/S1PR4 axis to the pathobiology of ovarian cancer." (PMID 31049165, 2019).
ovarian tumors (1 paper, 2019). "Thus, among all potential S1P/S1PR axes, the S1P/S1PR4 axis appears particularly relevant for T-cell infiltrates in immune high ovarian tumors and supports the role of S1P signaling in T-cell trafficking and/or survival." (PMID 31049165, 2019).
prostate carcinoma (1 paper, 2022). A carcinoma that arises from epithelial cells of the prostate gland. "Similarly, lipopolysaccharide was shown to stimulate prostate cancer cell invasion, progression, and metastasis via SPHK1/S1PR4/matriptase signaling, indicating that S1PR4 signaling is crucial for the progression of prostate cancer mediated by bacterial infection." (PMID 35565311, 2022).
type 1 diabetes mellitus (1 paper, 2019). A chronic condition characterized by minimal or absent production of insulin by the pancreas. "GSEA analysis also revealed that patients with obstructive CAD with higher expression levels of NCF2, MYO1F, S1PR4, and FCN1 in PBMC showed enriched pathways in viral myocarditis, Leishmania infection, type I diabetes mellitus, and hematopoietic cell lineage." (PMID 31245869, 2019).